DMPK (DM1 protein kinase)
Diseases named in the same sentence as DMPK in open-access papers (continued):
Sharing a sentence is not in itself a finding about the gene and the disease.
cancer (8 papers, 2018 to 2025). A tumor composed of atypical neoplastic, often pleomorphic cells that invade other tissues. "qRT-PCR analysis showed that the mRNA expression levels of TIMP1, CDC25C, ATP2A1, and TIGD1 were upregulated in cancer cell lines compared to normal cell lines, whereas NRG1 and DMPK exhibited reduced expression in cancer cell lines." (PMID 41190067, 2025). "Cytoband Chr19q13 is the human syntenic segment for chr7 in mice and contains both cancer-related and muscle disease-related genes (DMPK, DMWD, SIX5 related to Myotonic Dystrophy Type 1)." (PMID 38341433, 2024).
genetic disorder (8 papers, 2016 to 2026). "DM1 is a genetic disease caused by an abnormal unstable expansion of the CTG trinucleotide in the 3′UTR of the Myotonic Dystrophy Protein Kinase (DMPK) gene." (PMID 35008948, 2022). "DM1 is a genetic disorder caused by the expansion of CUG repeats in the 3’ UTR of DMPK transcripts, which leads to the dysregulation of other cellular transcripts." (PMID 26866591, 2016). "Since both DM1 and DM2 are genetic diseases, the diagnosis of DM can be made by genetic testing, addressing the presence of CTG or CCTG repeats in the DMPK or CNBP genes using blood samples." (PMID 36142405, 2022).
myopathy (8 papers, 2013 to 2024). A disease of the muscle in which the muscle fibers do not function properly. "However, those PMOs also target DMPK transcripts from the wild-type DMPK allele or other alleles containing C(C)TG repeat expansion, which may induce loss-of-function phenotypes, such as myopathy." (PMID 34948025, 2021). "It is postulated that myopathy and neuropathological changes in DM1 brain is caused by CTG trinucleotide expansion in the 3’ untranslated region of dystrophia myotonica protein kinase (DMPK) gene located on chromosome 19 and a repeat size of 50 or more is considered pathogenic in DM1." (PMID 35776705, 2022). "In this regard, DMPK knock-out mice fail to reproduce the multisystem phenotype of DM1 patients, and only develop late-onset myopathy, suggesting that haploinsufficiency of DMPK is not the primary mechanism that initiates this disease." (PMID 26217220, 2015). "However, if haploinsufficiency of DMPK is a relevant factor in DM1 pathology remains unclear as two different DMPK-knockout mouse models show either a late onset progressive myopathy or no muscular phenotype at all." (PMID 30425655, 2018).
tumor (6 papers, 2017 to 2023). "In this study we showed, for the first time, that DMPK has a role in VEGF-induced activation of MAPK in endothelial cells, as well as their proliferation and migration required for normal and tumor-associated angiogenesis." (PMID 29296234, 2017). "We also report that the pyrazolyl-urea GeGe3 blocks tumor angiogenesis through targeting DMPK activity and protein level." (PMID 29296234, 2017). "GeGe3 alters angiogenesis by targeting DMPK in tumor endothelial cells and pericytes." (PMID 29296234, 2017). "Additional screening revealed that compound could target Aurora B, Aurora C, NEK10, polo-like kinase (PLK2, PLK3), dystrophia myotonica protein kinases-1 (DMPK) and CAMK1, and the authors then speculated that GeGe-3 alters angiogenesis by targeting DMPK in tumor endothelial cells and pericytes." (PMID 32751358, 2020).
cardiac disease (2 papers, 2008 to 2022). "DMPK is involved in muscle function, and decreased DMPK expression has been linked to muscle impairment and cardiac disease in patients and mouse models." (PMID 35592702, 2022).
neurodevelopmental disorder (1 paper, 2017). A behavioral and cognitive disorder with onset during the developmental period that involves impaired or aberrant development of intellectual, motor, or social functions.
DMPK also shares sentences with these, for which no sentence is quoted: myotonic dystrophy type 2 (14 papers); fragile X syndrome (5); Huntington disease (5); Huntington disease-like 2 (5); neurological disorders (3); Cognitive impairment (2); dentatorubral-pallidoluysian atrophy (2); Friedreich ataxia (2); Prader-Willi syndrome (2); Rett syndrome (2); spinal muscular atrophy (2); spinocerebellar ataxia 36 (2); Spinocerebellar Ataxia 8 (2); spinocerebellar ataxia type 1 (2); -respiratory problems (1); Adult onset (1); allergic reactions (1); amyotrophic lateral sclerosis (1); brain tumor (1); Brugada syndrome (1); cardiac arrhythmias (1); cardiac conduction disorders (1); Cardio-cutaneous syndromes (1); centronuclear myopathy (1); cerebellar ataxia (1); channelopathies (1); cholelithiasis (1); colorectal cancer (1); congenital myopathy (1); Crouzon syndrome (1).
A further 36 diseases each share a sentence with DMPK in 1 paper.